RNU6-935P (RNA, U6 small nuclear 935, pseudogene)
Gene: Small nuclear RNA gene on chromosome X (50,649,641 to 50,649,740, forward strand). Ensembl gene ENSG00000222303.
Homologues: Orthologues: chimpanzee U6 (100% identical), macaque U6 (95% identical), dog U6 (75% identical), mouse Gm25834 (75% identical), pig U6 (74% identical), guinea pig U6 (68% identical). Paralogues in human: RNU6-520P (86% identical), RNU6-975P (86% identical), RNU6-16P (85% identical), RNU6-46P (85% identical), RNU6-480P (85% identical), RNU6-1316P (84% identical), RNU6-144P (84% identical), RNU6-333P (84% identical), RNU6-356P (84% identical), RNU6-487P (84% identical), RNU6-1031P (83% identical), RNU6-1040P (83% identical), and 1284 more.